SIRT1 (sirtuin 1)
Diseases named in the same sentence as SIRT1 in open-access papers (continued):
Sharing a sentence is not in itself a finding about the gene and the disease.
diabetic nephropathy (continued). "Importantly, it has been discovered that MA can trigger the AMPK/SIRT1 pathway to improve diabetic nephropathy." (PMID 39881825, 2025). "Indeed, quercetin can help prevent AGE accumulation and reduce diabetic nephropathy, while resveratrol activates the SIRT1 pathway, improving insulin sensitivity." (PMID 41150789, 2025). "In addition, inhibition of Cdk5 overactivation in our diabetic nephropathy model positively regulated the NGF/Sirt1 axis and reduced the HG-induced oxidative stress response and apoptosis in podocytes." (PMID 41181709, 2025). "The study also highlighted the role of Cdk5-mediated Sirt1 phosphorylation in mitochondrial dysfunction and podocyte injury in diabetic nephropathy, suggesting that targeting the Cdk5-Sirt1 signaling pathway could be a potential therapeutic strategy." (PMID 39835172, 2025). "Formononetin treatment has also been shown to enhance creatinine clearance, significantly reduce oxidative stress, and increase the renal expression of SIRT1, an anti-aging protein that is involved in diabetic nephropathy, in diabetic mouse and rat model animals." (PMID 41020857, 2025). "Furthermore, in diabetic nephropathy models, silencing SIRT1 protein promotes fibrosis and inflammation factor expression by upregulating HIF-1α protein, accelerating diabetic nephropathy progression, whereas overexpressing SIRT1 has the opposite effect." (PMID 39408861, 2024). "Furthermore, consistent with our results presented here, H2S attenuates homocysteine-induced mitochondrial ROS and improves respiration in osteoblastic cells, and in diabetic nephropathy, increases sirtuin 1 and decreases oxidative stress." (PMID 38229140, 2024). "SIRT1 inhibits EMT in diabetic nephropathy renal tubular cells via YY1 deacetylation." (PMID 39335456, 2024). "Although the exact details of renal regulation by GLP-1 are unknown, it has been found that GLP-1 ameliorates renal injury, fibrosis, and lipid accumulation in diabetic nephropathy rats via the Sirt1/AMPK/PGC1α pathway." (PMID 39598478, 2024). "According to an additional study, tropisetron may reduce oxidative damage and modify the levels of SIRT1, FOXO3a, and claudin-1, which could lessen renal damage brought on by diabetic nephropathy." (PMID 38629089, 2024). "By restoring the nuclear localization and transcriptional activity of FOXO1/3a, SIRT1 may facilitate the expression of target genes that protect against high glucose-induced mesangial cell injury in diabetic nephropathy." (PMID 39014438, 2024). "Similarly, lower expression levels of Sirt1 predicted albuminuria in patients with diabetic nephropathy." (PMID 36818747, 2023). "Meanwhile, SIRT1 is a key factor in the development of diabetic nephropathy pathology." (PMID 37553608, 2023). "Therefore, USP22 signaling in mesangial cells has beneficial effects on the pathogenesis of diabetic nephropathy via Sirt-1 stabilization." (PMID 36834633, 2023). "Meanwhile, salidroside may treat diabetic nephropathy in mice through SIRT1–PGC1α mediated mitochondrial biogenesis." (PMID 36430183, 2022). "The activation of AMPK/SIRT1 signaling pathway may affect the metabolism in the kidney of diabetic mice, thereby protecting the renal function and alleviating the symptoms of diabetic nephropathy." (PMID 35042497, 2022). "Notably, lncRNA TUG1 affected high glucose-stimulated renal epithelial cell injury via regulation of endoplasmic reticulum stress by targeting miR-29c-3p and SIRT1 in diabetic nephropathy." (PMID 36313695, 2022).
diabetic nephropathy (continued). "Taken together, dyslipidemia in diabetic nephropathy mice was ameliorated by the downregulation of HNF4A and activation of AMPK and SIRT1, which could be related to abnormal lipid metabolism in renal podocytes in diabetic nephropathy." (PMID 35480869, 2022). "Similarly, SIRT1 transgenic mice demonstrate ameliorated diabetic kidney disease (DKD) because of reduced levels of oxidative stress markers, while induced SIRT1-deficient mice show elevated kidney inflammation and urinary albumin excretion." (PMID 35277012, 2022). "Furthermore, one other group found that salidroside, an active component from Rhodiola rosea L., ameliorates diabetic nephropathy by stimulating the Sirt1/PGC-1α axis in diabetic mice." (PMID 35321238, 2022). "In addition, research on Resveratrol, an activator of SIRT1, and its impact on diabetic nephropathy, demonstrates Sirt1 expression in adult kidneys of humans, mice, and rats, with SIRT1 distribution seen in the nucleus of the glomeruli." (PMID 36139886, 2022). "Besides, MA protected against diabetic nephropathy and ischemia/reperfusion injury by activating the SIRT1/AMPK axis." (PMID 35265366, 2022). "Likewise, resveratrol protected against diabetic kidney disease in db/db mice with type 2 diabetes via an AMPK/SIRT1-independent mechanism." (PMID 35956292, 2022). "Our network pharmacology results indicated that baicalin might improve diabetic nephropathy through SIRT1, HNF4A, JAK3, and HMGCR." (PMID 35480869, 2022). "SIRT1 decreased in renal tubules and glomerulus of diabetic nephropathy patients." (PMID 35774140, 2022). "In addition, isoliquiritigenin also has a good therapeutic effect on kidney injury in diabetic nephropathy and treats renal fibrosis by regulating oxidative stress and inflammation mediated by the SIRT1 pathway." (PMID 35978370, 2022). "Furthermore, it was recently reported that short-term administration of NMN to 8-week-old diabetic nephropathy mice for 2 weeks enhanced Sirt1 expression in podocytes and continued to inhibit albuminuria in a glucose-independent manner until 24 weeks of age." (PMID 34439446, 2021). "TUG1 regulates miR-29c-3p/SIRT1 and subsequent ERS to relieve high glucose induced renal epithelial cells injury, and suggests a potential role for TUG1 as a promising diagnostic marker of diabetic nephropathy." (PMID 34097717, 2021). "Furthermore, some SIRT1 activators, including resveratrol, have been shown to inhibit development of diabetic nephropathy in mice." (PMID 33150239, 2020). "Indeed, one study showed that SIRT1 overexpression, specifically in proximal tubular cells, ameliorated progression of diabetic nephropathy in mice." (PMID 33150239, 2020). "Serum SIRT1 levels in diabetic nephropathy patients are also decreased significantly." (PMID 31637223, 2019). "By contrast, Sirt1 activation by theobromine protects the diabetic kidney and may have therapeutic potential for diabetic nephropathy." (PMID 28351995, 2017). "RVT also plays a role in the attenuation of diabetic nephropathy by activating SIRT1." (PMID 29104258, 2017). "Sirt1-deacetylase activity should decrease in diabetic nephropathy." (PMID 22028701, 2012). "Some studies have indicated that genistein supplementation may help regulate blood pressure by affecting renin secretion and inhibiting cellular apoptosis through inhibition of SIRT1 gene expression in common kidney diseases (diabetic nephropathy, hypertensive kidney disease, and renal fibrosis)." (PMID 39770942, 2024).
diabetic nephropathy (continued). "Therefore, activation of SIRT1 can be a protective mechanism in diabetic kidney disease." (PMID 38540101, 2024). "Therefore, we propose the scientific hypothesis: The CDK5 activity in diabetic nephropathy causes podocyte injury and apoptosis by regulating the NGF/Sirt1 axis and oxidative stress inflammatory factors in podocytes." (PMID 35874807, 2022). "However, the role of baicalin in diabetic nephropathy treatment and the regulation of SIRT1/AMPK/HNF4A pathway remains unclear and requires future studies." (PMID 35480869, 2022). "In the context of renal diseases, particularly in diabetic nephropathy, miR-34 has shown increased levels in mesangial and tubular cells treated with HG and was also increased in diabetic nephropathy mice and patients; these changes in tubular cells were attributed to SIRT1 regulation by miR-34a." (PMID 32887498, 2020). "Previous studies have found that Sirt1 is a protective factor of tubular cells and that Sirt1 expression was increased in both human and animal models of diabetic nephropathy (DKD) and confirmed to be protective in DKD kidneys." (PMID 29848325, 2018). "Furthermore, Sirt1-induced autophagy activation may contribute to Sirt1-mediated renoprotective effect in diabetic nephropathy." (PMID 22028701, 2012). "Moreover, recent evidence suggests that SGLT2 inhibitors, now a mainstay therapy for diabetic nephropathy, may exert part of their renoprotective effects through restoration of renal SIRT1 activity and improvement of mitochondrial integrity, thereby indirectly modulating NAD+ metabolism." (PMID 41470091, 2025). "The inverse regulation of SIRT1 and CD38 underscores a dysfunctional NAD+-SIRT1 signaling disruption that undermines mitochondrial resilience in diabetic nephropathy." (PMID 41470091, 2025). "Research has demonstrated that SIRT1 can activate the Nrf2/ARE signaling pathway, thereby alleviating oxidative stress in diabetic nephropathy and preventing the progression of renal fibrosis." (PMID 39335456, 2024). "RUNX3 activated Apelin and regulated the SIRT1/FOXO signaling pathway, resulting in the suppressed cell proliferation and fibrosis in diabetic nephropathy." (PMID 39014438, 2024). "Isoliquiritigenin mitigates inflammatory responses by upregulating Sirt-1 activity and modulating the NF-κB and NLRP3 pathways, leading to reduced collagen accumulation in diabetic kidney disease and safeguarding renal architecture and functionality." (PMID 39911234, 2024). "USP22 in podocytes promotes diabetic nephropathy by enhancing oxidative stress, while USP22 in mesangial cells suppresses fibrosis through the stabilization of Sirt-1." (PMID 36834633, 2023). "Further, free radicals induced during diabetic nephropathy lowered the activity of AMPK and SIRT1, the critical regulators of PGC1α activity and energy metabolism of mitochondria." (PMID 35956292, 2022). "Our results proved the new role of HNF4A mediated by SIRT1 and AMPK signaling pathways in the lipid metabolism of diabetic nephropathy." (PMID 35480869, 2022). "In vitro, NAD+ supplementation of glomerular mesangial cells incubated with high glucose confirmed activation of the SIRT1 and AMPK pathways and protected the cells from hypertrophy, an early manifestation of diabetic nephropathy." (PMID 36611814, 2022). "Genipin-1-β-D-gentiobioside efficiently suppressed inflammation and oxidative stress, thus improving renal function in a model of diabetic nephropathy, partly via AMPK/SIRT1 activation and NF-κB inhibition." (PMID 35883477, 2022). "Salidroside can also regulate the SIRT1/PGC-1α signaling pathway to improve mitochondrial dysfunction, reduce renal fibrosis in diabetic nephropathy, and protect renal function." (PMID 35978370, 2022).
diabetic nephropathy (continued). "In diabetic kidney disease, metformin relieved oxidative stress and enhanced autophagy via the AMPK/SIRT1 Foxo1 pathway." (PMID 36081940, 2022). "Maslinic acid ameliorates diabetic nephropathy and activates the renal AMPK/SIRT1 signaling pathway." (PMID 35042497, 2022). "For instance, SIRT1 deacetylated FOXO1 to combat oxidative stress in diabetic vascular complications, diabetic nephropathy, and particularly in diabetic cardiomyopathy under the treatment of resveratrol." (PMID 33304318, 2020). "Additionally, in diabetic kidney disease, metformin affects the AMPK/SIRT1 pathway to relieve oxidative stress and enhance autophagy." (PMID 39881825, 2025). "Most large-scale studies suggest that serum SIRT1 is diminished in type 2 diabetic patients, regardless of concomitant diabetic nephropathy." (PMID 41009597, 2025). "Further studies are needed to uncover whether Sirt1/Claudin-1 is important in the early stages and whether Nampt/Sirt6/TIMP-1 is significant in the middle to late stages of human diabetic nephropathy, similar to that in murine models." (PMID 38587753, 2024). "In summary, RES reduces renal fibrosis and restores renal function by regulating the AMPK/SIRT1/NOX 4/ROS signaling pathway, achieving prevention and control of diabetic nephropathy, and reducing the immune-inflammatory damage of the kidneys caused by diabetes." (PMID 38962006, 2024). "Indeed, in several experimental models, including diabetic nephropathy and renal fibrosis induced by unilateral ureteral obstruction (UUO), SIRT1 is described as a therapeutic target, reducing endoplasmic reticulum stress and fibrosis." (PMID 38114708, 2023). "Finally, in the context of diabetic nephropathy, supplementation of STZ-treated spontaneously hypertensive rats with theobromine, a non-polyphenolic component of cocoa, restored NAD+ levels and SIRT1 activity." (PMID 36611814, 2022). "In addition to ameliorating insulin assistance, SIRT1 has also been known to promote the activation of the Nrf-2/ARE pathway and improve oxidative stress in diabetic nephropathy." (PMID 34845191, 2021). "In summary, our study uncovers a lncRNA TUG1—miR-29c-3p - SIRT1 network in regulating high glucose-induced apoptosis via ERS in renal epithelial cells, which can hopefully be beneficial to the pharmacological intervention of diabetic nephropathy." (PMID 34097717, 2021). "In vitro studies using human proximal tubular cells (HRCE) exposed to high glucose conditions (30 mM, for 1–6 h) showed that probucol activates AMPK/Sirt1 pathway and inhibits p66Shc expression and ROS generation by phosphorylation of AMPK in diabetic nephropathy." (PMID 34685718, 2021). "SIRT1 (NAD-dependent deacetylase sirtuin-1) is abundant in kidney, which is closely related to renal physiology and pathology, and involved in the regulation of diabetic nephropathy." (PMID 34097717, 2021). "Diabetic kidney disease reveals an important impairment of adenosine monophosphate- activated protein kinase (AMPK) and sirtuin-1 (SIRT1) signaling, which may contribute to the development and progression of nephropathy." (PMID 32549243, 2020). "However, some studies have found that knockdown of miR-133b and miR-199b alleviates diabetic nephropathy, renal fibrosis, and TGF-β1-induced EMT through sirtuin 1 (SIRT1)." (PMID 31481100, 2019). "SIRT1 and FOXO1 play an important role in the pathogenesis of diabetic nephropathy (DN)." (PMID 28860538, 2017). "Nevertheless, there were only a very limited number of studies that have characterized SIRT1 genes for DN in Japanese Caucasians, while no study focused on the association between FOXO1 gene and diabetic nephropathy." (PMID 28860538, 2017).
diabetic nephropathy (continued). "Finally, the BMAL1/SIRT1/PGC-1α mitophagy pathway appears to protect podocytes, specialized cells of the Bowman’s capsule that encase the glomerular capillaries, under high glucose conditions, a major contributor to the pathogenesis of diabetic nephropathy." (PMID 40705152, 2025). "In addition, the nephroprotection of SIRT1 in diabetic nephropathy is mediated by deacetylation of some transcription factors, including FoxO, RelA/NF-kβ, STAT-3, and PGC-1α/PPARγb, etc., and the higher activity of SIRT1 exerts the renal protective effect for diabetic kidney disease." (PMID 40649025, 2025). "Moreover, activation of the SIRT1-PGC-1α-TFAM pathway in placenta-derived mesenchymal stem cells restores PINK1/PARKIN-mediated mitophagy following podocyte injury, thereby helping to slow the progression of diabetic nephropathy." (PMID 40705152, 2025). "Furthermore, in a diabetic mouse model, elevated SIRT1 protein levels in liver, muscle, and fat cells were found to enhance the high-density lipoprotein (HDL) cholesterol function and prevent the development of diabetic kidney disease." (PMID 39337411, 2024). "Moreover, activation of SIRT1 in the kidneys of diabetic mice could elevate NRF2 antioxidant signaling and provide remarkable protection against diabetic nephropathy-induced renal oxidative stress." (PMID 36899375, 2023). "Augmentation of mitochondrial biogenesis and mitophagy through AMPK/Sirt1/peroxisome proliferator-activated receptor-gamma coactivator 1 alpha (PGC-1α) signaling pathway has been protective against proteinuria and podocyte injury in a mouse model of diabetic nephropathy." (PMID 36818747, 2023). "Consistently, inhibition of AMPK or Sirt1 or downregulation of PGC-1α with a siRNA significantly reduced ATP production and downregulated the expression of mitochondrial biogenesis markers such as Nrf-1 and mitochondrial factor A (TFAM) in a mouse model of diabetic nephropathy." (PMID 36818747, 2023). "Our results, however, do not prove that NMN accumulation is the cause of diabetic nephropathy, but rather that NAD+ metabolism is a disorder, whether NMN can bind alone or influence Sirt1 needs further study." (PMID 35408818, 2022). "Furthermore Sirt1 is one of the substrates of CDK5, which plays an important protective role in cell differentiation, survival, and anti-oxidation in diabetic nephropathy." (PMID 35874807, 2022). "In addition, SIRT1-AMPK-PGC-1α pathway exerts its anti-oxidative activity in other diabetic vascular complications including brain complications, diabetic cardiomyopathy, and diabetic nephropathy." (PMID 33304318, 2020). "Therefore, the primary purpose of this review is to summarize the recent advances regarding the effects and related epigenetic mechanisms of SIRT1 in diabetic complications, including diabetic cardiomyopathy (DCM), diabetic nephropathy (DN), and diabetic retinopathy (DR)." (PMID 33537003, 2020). "Therefore, our results suggest that the SNPs within SIRT1 and FOXO1 might be involved in the process of diabetic nephropathy in Henan Han Chinese population." (PMID 28860538, 2017). "Previous studies have reported SIRT1 was inversely modulated by miR‐34a, However, mechanism of metformin (MFN)'s renal podocyte protection under high glucose (HG) conditions and the connection between miR‐34a and SIRT1 expression in diabetic nephropathy (DN) remain unclear." (PMID 38270305, 2024).